ITGA8 (integrin subunit alpha 8)
Diseases named in the same sentence as ITGA8 in open-access papers (continued):
Sharing a sentence is not in itself a finding about the gene and the disease.
infection (2 papers, 2012 to 2017). The state of being infected such as from the introduction of a foreign agent such as serum, vaccine, antigenic substance or organism. "Of the genes participating in metal ion binding (MIB1, KAT6B, ITGA8, HBAC, KCNC1, and F13A), most were downregulated during the later stages of GCRV infection, whereas genes involved in protein ubiquitination (HERC1 and HERC4) were upregulated during the later stages of infection." (PMID 28906455, 2017).
kidney diseases (2 papers, 2024). "We speculate that some ITGA8-positive plasma-derived sEVs came from kidney mesangial cells and could be utilized for liquid biopsy to detect kidney diseases." (PMID 38436899, 2024). "Our findings hold significance as they reveal variations in the immunoexpression of ITGA8 and VANGL2 throughout typical human kidney development and in renal disorders." (PMID 39064873, 2024).
cardiovascular diseases (1 paper, 2023). "Combined with recently generated BAC transgenic Myh11-CreERT2-RAD mice and the Itga8-CreERT2 mouse models, our models will help expand the research toolbox, facilitating unbiased and comprehensive research in SMCs and SMC-dependent cardiovascular diseases." (PMID 37289544, 2023).
neurological diseases (1 paper, 2024). "MBD5, OGDHL, AUTS2, EGR3, QPCT, and ITGA8 are linked to neurological diseases." (PMID 39588153, 2024).
ITGA8 also shares sentences with these, for which no sentence is quoted: cardiomyopathies (2 papers); adenocarcinoma (1); cardiac hypertrophy (1); Cognitive impairment (1); colorectal cancer (1); diabetes (1); endothelial dysfunction (1); germ cell tumor (1); glioblastoma (1); hypoplastic left heart syndrome (1); liposarcoma (1); lung squamous cell carcinoma (1); lupus (1); malaria (1); meningioma (1); multiple sclerosis (1); non-small cell lung carcinoma (1); osteosarcoma (1); polyp (1); renal carcinoma (1); renal cell carcinoma (1).